VGLL3 (vestigial like family member 3)
Description:
May act as a specific coactivator for the mammalian TEFs.
Synonyms: Vgl-3; VGL3
Tractability: PROTAC: UniProt records ubiquitination sites on it; ubiquitination databases record sites on it.
Gene: Protein-coding gene on chromosome 3 (86,876,388 to 86,991,149, reverse strand). Ensembl gene ENSG00000206538.
Subcellular location: Nucleus
Subcellular location (Human Protein Atlas): Cytosol; Nucleoli
Gene Ontology:
Biological process: regulation of transcription by RNA polymerase II; regulation of DNA-templated transcription
Cellular component: nucleus
Genetic constraint (gnomAD): Loss-of-function variants: 16 observed, 26.03 expected, observed/expected ratio (o/e) 0.61, 90% interval 0.41 to 0.93. The upper end of that interval is the gene's LOEUF score, 0.93, which puts it in group 3 of 6, group 1 being the genes least tolerant of losing a copy. Missense variants: 426 observed, 395.49 expected, observed/expected ratio (o/e) 1.08, 90% interval 0.99 to 1.17. Synonymous variants: 177 observed, 145.68 expected, observed/expected ratio (o/e) 1.22, 90% interval 1.07 to 1.38.
Homologues: Orthologues: chimpanzee VGLL3 (100% identical), macaque VGLL3 (98% identical), rabbit VGLL3 (94% identical), pig VGLL3 (91% identical), mouse Vgll3 (89% identical), rat Vgll3 (89% identical), guinea pig VGLL3 (85% identical), dog VGLL3 (82% identical), tropical clawed frog cfap70 (61% identical), zebrafish vgll3 (42% identical), Drosophila melanogaster vg (24% identical). Paralogues in human: VGLL2 (37% identical), VGLL1 (21% identical).
Diseases named in the same sentence as VGLL3 in open-access papers:
VGLL3 is named in the same sentence as 59 diseases in open-access papers, as found by Europe PMC text mining. Sharing a sentence is not in itself a finding about the gene and the disease. The quoted sentences say what the papers report.
autoimmune disease (11 papers, 2017 to 2025). A disorder resulting from loss of function or tissue destruction of an organ or multiple organs, arising from humoral or cellular immune responses of the individual to their own tissue constituents. "Beyond fibrosis, VGLL3 is also widely expressed in various tissues and implicated in multiple disease processes, including cancer and autoimmune disorders." (PMID 41008580, 2025). "It is worth noting that whereas VGLL3 seems to be enriched in the skin of women and is associated with female-biased autoimmune diseases, YAP1 is associated with pro-oncogenic signaling, and the incidence of cancer is higher in men." (PMID 40741215, 2025). "We also tentatively identified an association between CR with VGLL3, which is reported to be associated with autoimmune diseases." (PMID 37926851, 2023). "Therefore, the heightened expression of BAFF due to VGLL3 may predispose women to autoimmune disorders with directly or indirectly impacted metabolic reprogramming." (PMID 38726338, 2024). "Thus, the LLPS of VGLL3 may also be involved in the development of autoimmune diseases and associated fibrosis." (PMID 36754961, 2023). "VGLL3 is overexpressed in cancer cells, such as those from breast tumors and osteosarcomas, and is involved in autoimmune diseases, including lupus, scleroderma, and Sjögren’s syndrome." (PMID 41008580, 2025). "The expression level of VGLL3 is further upregulated in autoimmune diseases, including systemic lupus erythematosus (SLE), SS, and rheumatoid arthritis (RA)." (PMID 38726338, 2024). "Vestigial-like family member 3 (VGLL3) has emerged as a potential driver for autoimmune disease as well as its female bias." (PMID 38726338, 2024). "In RA, a female-biased autoimmune disease, VGLL3 has been shown to modulate the expression of Hippo “off” pathway molecules WWTR1 (TAZ) and AMOTL2 in patient-derived fibroblast-like synoviocytes." (PMID 38726338, 2024). "Interestingly, associations with similar traits (pubertal timing, pubertal growth spurt) have been detected with the human ortholog (VGLL3) and VGLL3 has also been identified as a promoter of sex-biased autoimmune diseases." (PMID 40176157, 2025). "As VGLL3 levels are upregulated in a number of autoimmune diseases, it will be of future interest to determine whether changes in metabolic states lead to hypomethylation in VGLL3 to impact disease pathogenesis." (PMID 38726338, 2024). "Understanding the multifaceted roles of VGLL3 in nutrient sensing and immune modulation provides insight into the fundamental question of sexual dimorphism in immunometabolism and sheds light on potential therapeutic targets for autoimmune diseases." (PMID 38726338, 2024). "Recently, the role of VGLL3 in autoimmune diseases has drawn much attention." (PMID 35941675, 2022). "In humans, VGLL3 is a putative transcription factor that has recently been found to regulate female-biased inflammatory processes, possibly also playing a role in autoimmune diseases with a difference in sex prevalence." (PMID 29096703, 2017). "Considering the suggested link between adipocyte-associated chronic inflammation and autoimmunity, there is significant interest in studying the immunometabolic role of VGLL3-IL-1ɑ signaling in SLE and additional autoimmune diseases." (PMID 38726338, 2024). "The upregulation of VGLL3 in SLE is seen in both female and male patients, suggesting its broad role in activating autoimmune disease pathways." (PMID 38726338, 2024). "In turn, these Hippo pathway molecules mediate the regulation of interferon regulatory factor 3 (IRF3) and IFN-β1 by VGLL3, suggesting that VGLL3 receives signal from the Hippo stress-sensing pathway to activate IFN responses, a key immunological pathway in autoimmune disease." (PMID 38726338, 2024).
sarcoma (8 papers, 2019 to 2025). A usually aggressive malignant neoplasm of the soft tissue or bone. "After a brief in vitro expansion at 1% oxygen, MSCs were transformed into sarcoma cells via overexpression of Ccne1 or Vgll3, using viral vectors which also encode a red fluorescent protein (dsRED) reporter for tracing." (PMID 38509063, 2024). "It resides in chromosome 3p11-12 region near VGLL3 gene, which shows amplification in diverse sarcomas." (PMID 37090158, 2023). "VGLL3 gene amplification and overexpression were found in myxoinflammatory fibroblastic sarcoma and soft tissue sarcoma." (PMID 32793503, 2020). "Recent deep sequencing of myxoinflammatory fibroblastic sarcoma demonstrated that VGLL3 amplification is a highly recurrent feature of this type of sarcoma." (PMID 32793503, 2020). "VGLL1 dysregulation was detected in various types of tumor; however, gene alterations in VGLL2 and VGLL3 were observed specifically in sarcoma." (PMID 32793503, 2020). "However, recent genetic analyses of various forms of sarcoma show VGLL3 gene amplifications and fusions, consistent with our identification of VGLL3 as an oncogene." (PMID 38213996, 2024). "Furthermore, VGLL3 gene amplification has been observed in several types of sarcomas, and VGLL3 has been shown to promote tumour cell growth." (PMID 35366053, 2022). "In addition to sarcoma, VGLL3 expression was found to be positively correlated with accelerated grade and poor prognosis in gastric tumor." (PMID 32793503, 2020). "Similarly to VGLL2, VGLL3 gene alterations were identified in sarcoma." (PMID 32793503, 2020). "Accordingly, the immune-infiltrated Vgll3+ model showed a more robust response to the standard regimen of doxorubicin compared to the immune-excluded Ccne1+ model, suggesting that an inflamed sarcoma microenvironment may be favorable for chemotherapy responses." (PMID 38509063, 2024).
breast carcinoma (7 papers, 2015 to 2025). "Transcription cofactor vestigial-like protein 3 (VGLL3) is a coactivator of mammalian toxicity equivalency factors (TEFs), and was associated with breast cancer, colon cancer, and lung cancer among other malignancies." (PMID 31992826, 2020). "Among the ER + Luminal type A/B breast cancers, VGLL3 expression negatively correlated with ERα status." (PMID 35217640, 2022). "We previously found that VGLL3 is highly expressed in mesenchymal cancer cells, such as breast cancer MDA‐MB‐231 cells." (PMID 35366053, 2022). "Previously, VGLL3 has been shown to enhance breast cancer cell proliferation and drive systemic autoimmunity." (PMID 36347861, 2022). "Collectively, these data provide in vivo evidence supporting VGLL3 as a YAP-TEAD target gene in breast cancers." (PMID 35217640, 2022). "We next explored the clinical relevance of VGLL3 in ER+ breast cancer." (PMID 35217640, 2022). "Moreover, histone deacetylase inhibitors, such as Entinostat, induce VGLL3 expression to inhibit ER+ breast cancer cells." (PMID 35217640, 2022). "VGLL3 was significantly downregulated in Luminal Type B breast cancers." (PMID 35217640, 2022). "VGLL3 or HMGA2 knockdown repressed the motility of the mesenchymal breast cancer MDA‐MB‐231 cells." (PMID 35366053, 2022). "Moreover, low VGLL3 expression was associated with reduced survival in ER+ but not in other types of breast cancers." (PMID 35217640, 2022). "VGLL3 is also involved in EMT‐like phenotypes in TGF‐β‐stimulated cells and mesenchymal breast cancer cells." (PMID 35366053, 2022). "And in estrogen receptor alpha (ERα) positive breast cancer, YAP upregulates vestigial like family member 3 (VGLL3), recruiting the nuclear receptor co-repressor (NCOR2/SMRT) repressor to the estrogen receptor 1 (ESR1) super-enhancer, thereby silencing ERα transcription and inhibiting tumor growth." (PMID 40673277, 2025). "Interestingly, we also observed a strong positive correlation between VGLL3 expression with either CTGF or CYR61 mRNA in multiple cancer types, including breast cancer." (PMID 35217640, 2022). "Furthermore, comparisons of relative VGLL gene expression revealed VGLL3 and VGLL4 were abundantly expressed across different breast cancer subtypes." (PMID 28733631, 2017).
Autoimmunity (6 papers, 2019 to 2025). The occurrence of an immune reaction against the organism's own cells or tissues. "Combined, VGLL3’s regulation of immune and metabolic networks supports the idea that it regulates sexually dimorphic immune regulation and contributes to the increase in risk of autoimmunity for women." (PMID 38726338, 2024). "The observations that VGLL3 is both elevated in normal female skin cells and activates inflammatory pathways key to lupus pathogenesis suggest its role in predisposing females to autoimmunity." (PMID 38726338, 2024). "However, a sex-linked autoimmunity phenotype has been reported recently for Vgll3−/− mice." (PMID 31138678, 2019). "In summary, recent research has identified an autoimmunity-prone transcriptional signature in the skin orchestrated by the female skin–enriched transcription coregulator VGLL3." (PMID 40741215, 2025). "However, hyperactivation of the VGLL3-mediated energy-sensing pathway can lead to inflammatory cell death and the development of autoimmunity." (PMID 38726338, 2024). "However, the excessive activation of the VGLL3-mediated energy-sensing pathway can trigger inflammatory cell death and the exposure of self-antigens, leading to the onset of autoimmunity." (PMID 38726338, 2024). "Vestigial-like family member 3 (VGLL3), a female-biased factor that promotes autoimmunity, has recently been discovered to assist cells in sensing and adapting to nutritional stress." (PMID 38726338, 2024).
lupus (6 papers, 2019 to 2025). "Transgenic mice with epidermal overexpression of VGLL3 develop lupus-like systemic disease and provide a tool for identifying therapeutic targets and investigating how epithelial–immune cell interactions precipitate systemic autoimmunity." (PMID 40741215, 2025). "In skin biopsies from patients with lupus, VGLL3 localization was nuclear in both sexes, suggesting activation of this autoimmune pathway in disease regardless of sex." (PMID 40741215, 2025). "In human keratinocytes, reduction in VGLL3 levels downregulates genes that are hyperactivated in lupus skin." (PMID 38726338, 2024). "Genome-wide, VGLL3 targets are enriched for genes dysregulated in lupus, scleroderma, and Sjögren’s syndrome." (PMID 32030371, 2019). "Significantly increased mRNA expression of eleven inflammatory and lupus-related markers was observed in the skin of VGLL3 overexpressing mice compared to wild type mice." (PMID 32030371, 2019). "VGLL3-overexpressing mice had higher rates of developing lupus-like cutaneous phenotype." (PMID 35941675, 2022). "The lupus-like phenotypes in the Vgll3-transgenic mice raise the question whether VGLL3 also sensitizes skin to UV radiation." (PMID 32030371, 2019). "Research has demonstrated that overexpression of VGLL3 in females can trigger cutaneous and systemic autoimmune diseases resembling systemic lupus erythematosus (SLE)." (PMID 38348744, 2024). "VGLL3 was also required in the IFN-α-induced BAFF expression and pathogenesis of systemic lupus erythematosus (SLE)." (PMID 35941675, 2022).
lung carcinoma (4 papers, 2020 to 2024). "VGLL3 acts as a coactivator of mammalian toxicity equivalency factors and is implicated in many kinds of cancers, including breast, colon, and lung cancers." (PMID 36245988, 2022).
prostate carcinoma (3 papers, 2014 to 2016). A carcinoma that arises from epithelial cells of the prostate gland. "Measurements of VGLL3 expression levels showed larger variation between biopsies, which mainly was caused by a low expression level in prostate cancer cells compared to the other two signature genes." (PMID 25296164, 2014). "Multiple biopsy samples from 43 patients were evaluated using a previously reported gene signature of IGFBP3, F3 and VGLL3 with potential prognostic value in estimating overall survival at diagnosis of prostate cancer." (PMID 25296164, 2014). "The gene expression levels of IGFBP3 and F3 in prostate cancer epithelial cell-containing tissue representing the primary and secondary Gleason patterns were high and consistent, while the low expressed VGLL3 showed more variation in its expression levels." (PMID 25296164, 2014). "A previously reported expression signature of three genes (IGFBP3, F3 and VGLL3) was shown to have potential prognostic value in estimating overall and cancer-specific survivals at diagnosis of prostate cancer in a pilot cohort study using freshly frozen Fine Needle Aspiration (FNA) samples." (PMID 26731648, 2016). "A recent report from our laboratory showed that a gene expression signature of IGFBP3, F3 and VGLL3 could estimate prostate cancer patients' overall survival at the time of diagnosis." (PMID 25296164, 2014). "It was further observed that the mean Ct values of IGFBP3, F3 and VGLL3 of all 97 cancer sample measurements were 28.7, 28.3 and 33.2 respectively, meaning that VGLL3 generally had lower expression levels compared to IGFBP3 and F3 in prostate cancer samples." (PMID 25296164, 2014).
serous ovarian carcinomas (3 papers, 2019 to 2023). "Comparison of VGLL3 protein expression in high-grade serous ovarian carcinoma and normal adjacent tissues." (PMID 37342190, 2023). "VGLL3 has been recognized as a tumor suppressor gene in serous ovarian carcinomas and stomach adenocarcinoma." (PMID 38026637, 2023). "VGLL3 protein expression in high-grade serous ovarian carcinoma according to the clinicopathological characteristics." (PMID 37342190, 2023). "Interestingly, the expression of VGLL3 was absent in high-grade serous ovarian carcinomas (HGSC), suggesting VGLL3 might also be involved in tumor suppressor pathways." (PMID 31799250, 2019).
soft tissue sarcoma (3 papers, 2019 to 2021). A malignant neoplasm arising from muscle tissue, adipose tissue, blood vessels, fibrous tissue, or other supportive tissues excluding the bones. "VGLL3, as a member of vestigial like family of proteins, is associated with epithelial OC and soft tissue sarcoma." (PMID 33563317, 2021). "Knockdown experiments showed that VGLL3 is required for proliferation in a soft tissue sarcoma-derived cell line." (PMID 32793503, 2020).
stomach adenocarcinoma (3 papers, 2020 to 2023). "VGLL3 is of interest as it may act as a tumor suppressor gene in epithelial ovarian cancer, but VGLL3 expression is a marker for poor outcome in stomach adenocarcinoma and in PCa." (PMID 34768683, 2021).
colon carcinoma (2 papers, 2016 to 2020). "VGLL3 (f70 kb away) encodes a colon carcinoma-related protein." (PMID 27906997, 2016).
melanoma (2 papers, 2022 to 2024). A malignant, usually aggressive tumor composed of atypical, neoplastic melanocytes. "Amongst YAP1/TAZ target genes overexpressed in both YAP5SA melanoma cell lines, only VGLL3 scored as essential in untreated YAP5SA melanoma cells." (PMID 35798875, 2022).
myocardial infarction (2 papers, 2023 to 2025). Gross necrosis of the myocardium, as a result of interruption of the blood supply to the area, as in coronary thrombosis. "Consistently, cardiac fibrosis after myocardial infarction is significantly attenuated in Vgll3-deficient mice, with increased miR-29b expression." (PMID 36754961, 2023). "In cardiac fibrosis, VGLL3 knockout significantly reduced the degree of fibrosis after myocardial infarction in mice and improved cardiac function." (PMID 41008580, 2025). "While the VGLL3-based early fibrosis detection platform constructed in this study has achieved preliminary validation in a mouse model of myocardial infarction, it still has limitations." (PMID 41008580, 2025). "Quantitative analysis showed a significant increase in VGLL3-positive area in myocardial infarction hearts compared to controls (p < 0.001)." (PMID 41008580, 2025). "Here authors reveal the mechanosensitive nuclear translocation of VGLL3, where it phase separates and promotes collagen production, and show that its knock-out is protective after myocardial infarction." (PMID 36754961, 2023). "Although we focused on substrate stiffness-induced Vgll3 expression, Vgll3 was rapidly induced even in the mouse heart, where there are few ECM proteins that generate matrix stiffness, upon myocardial infarction (3 days after MI)." (PMID 36754961, 2023).
schwannoma (2 papers, 2025). A benign, usually encapsulated slow growing tumor composed of Schwann cells. "It has also been reported that the majority of hybrid schwannoma–perineuriomas harbor VGLL3 rearrangements." (PMID 40218204, 2025). "In our cohort, we rapidly classified an intracranial schwannoma within minutes of sequencing and demonstrated a novel pathognomonic VGLL3 fusion within 24 hours." (PMID 40392954, 2025).
alveolar rhabdomyosarcoma (1 paper, 2019). A rapidly growing malignant mesenchymal neoplasm. "Finally, Vgll3 expression is 2.3-fold higher in mouse embryonal rhabdomyosarcomas caused by YAP1 S127A expression in activated satellite cells than in control skeletal muscle." (PMID 31138678, 2019). "This showed that average VGLL3 expression is highest in PAX3-FOXO1 alveolar rhabdomyosarcomas when compared to other forms of rhabdomyosarcoma, fetal myoblasts or differentiated muscle." (PMID 31138678, 2019). "In disease settings, VGLL3 was also highly expressed in dystrophic muscle and alveolar rhabdomyosarcoma." (PMID 31138678, 2019). "We found that mouse Vgll3 was expressed at low levels in healthy muscle but that its levels increased during hypertrophy or regeneration; in humans, VGLL3 was highly expressed in tissues from patients with various muscle diseases, such as in dystrophic muscle and alveolar rhabdomyosarcoma." (PMID 31138678, 2019). "Given that alveolar rhabdomyosarcomas (ARMS) frequently carry PAX3-FOXO1 or PAX7-FOXO1 fusion genes, we also analysed VGLL3 expression in ARMS." (PMID 31138678, 2019).